SIRT1 (sirtuin 1)
Diseases named in the same sentence as SIRT1 in open-access papers (continued):
Sharing a sentence is not in itself a finding about the gene and the disease.
liver fibrosis (continued). "Recent studies have demonstrated that the SIRT1/Nrf2 pathway is involved in various in vivo liver fibrosis models." (PMID 41498016, 2025). "It has been reported that Notch1 signal transduction is a downstream effector pathway of SIRT1, which can affect the progression of liver fibrosis, acute lung injury, and osteoporosis." (PMID 41333237, 2025). "During the progression of liver fibrosis, SIRT1 expression is downregulated, which concurrently disrupts lipid metabolism, exacerbates inflammation, and promotes ECM deposition." (PMID 41281762, 2025). "The Sirt1 pathway is involved in curcumin-induced endoplasmic reticulum stress-mediated necroptosis in hepatic stellate cells, leading to the alleviation of liver fibrosis." (PMID 40160465, 2025). "Overall, SIRT1 plays a critical protective role against liver fibrosis, and modulating SIRT1 represents a promising therapeutic strategy for liver fibrosis." (PMID 41281762, 2025). "The use of SIRT1-adenovirus vectors has been shown to increase SIRT1 expression in liver fibrosis models, leading to reduced oxidative stress, decreased fibrosis, and improved liver function." (PMID 40052151, 2025). "Studies have demonstrated that SIRT1 activation reduces liver fibrosis and inflammation in response to chronic ethanol exposure." (PMID 40052151, 2025). "We studied a SIRT1/2 inhibitor, Tenovin-1, as a novel intervention for the treatment of hepatic fibrosis in diabetic rats." (PMID 38993557, 2024). "In liver fibrosis treatment research, when exposed to TGFβ1, SIRT1 activation substantially decreased EZH2 acetylation levels." (PMID 37985432, 2024). "The induction of IL‐1β was further amplified by threefold in SIRT1 LKO mice, suggesting the presence of NLRP3+ cells and elevation of IL‐1β as key pathological features of liver fibrosis associated with SIRT1 loss." (PMID 36999514, 2023). "Age‐dependent inhibition of the longevity factor SIRT1 causes induction of the NLRP3 inflammasome and leads to severe and persistent liver fibrosis in old mice even after the cessation of liver injury." (PMID 36999514, 2023). "We believe that this is related to alleviating liver fibrosis and reducing intestinal permeability by overexpression of SIRT1." (PMID 37057212, 2023). "Collectively, progressive liver fibrosis during aging is likely attributed to pronounced suppression of SIRT1, induction of TGF‐β1‐sensitized HSCs, and aberrant ECM remodeling." (PMID 36999514, 2023). "In the present study, prolonged inhibition of SIRT1 results in persistent activation of NLRP3 and triggers the production of pro‐inflammatory cytokines, such as IL‐1β, in age‐associated liver fibrosis." (PMID 36999514, 2023). "We demonstrate, for the first time to our knowledge, that age‐dependent loss of SIRT1 is linked to activation of the NLRP3 inflammasome and perpetuates the progression of liver fibrosis." (PMID 36999514, 2023). "Strikingly, hepatocyte‐specific SIRT1 ablation caused aberrant HSC activation and severe liver fibrosis in young mice after liver injury, mimicking age‐associated liver fibrosis." (PMID 36999514, 2023). "In conclusion, the present study defines the mechanism by which age‐related SIRT1 loss induces the NLRP3 inflammatory pathway and promotes severe and persistent liver fibrosis during aging." (PMID 36999514, 2023). "In multiple experimental murine models of liver fibrosis, we compared the development of liver fibrosis in young and old mice, as well as in liver‐specific SIRT1 knockout (SIRT1 LKO) mice and wild‐type (WT) mice." (PMID 36999514, 2023). "We characterized a functional link of age‐mediated defects in SIRT1 to the NLRP3 inflammasome during age‐related liver fibrosis." (PMID 36999514, 2023). "Notch1 signaling has been stated as a downstream effector pathway of SIRT1 to affect disorder progressions, such as liver fibrosis." (PMID 37934372, 2023).
liver fibrosis (continued). "Animal experiments also found that Gardeniae Fructus can reduce thioacetamide-induced liver fibrosis in mice through the AMPK/SIRT1/NF-κB and Nrf2 signal pathways." (PMID 36248427, 2022). "Selenium-glutathione probiotic can effectively attenuate liver fibrosis by activating SIRT1 signaling and attenuating hepatic oxidative stress, endoplasmic reticulum stress, inflammation, and mitogen-activated protein kinase (MAPK) signaling." (PMID 35745140, 2022). "Previous studies have reported the role of Sirt1 in liver fibrosis by the inhibition of activated HSCs through its unique role of histone demethylation or histone deacetylation by targeting PPAR in HSCs." (PMID 36670959, 2022). "HSCs specific knockout of Sirt1 impaired the ameliorative effect of curcumol on hepatic fibrosis in mice." (PMID 35582617, 2022). "Specific knockdown of Sirt1 by HSCs in male ICR mice further exacerbated CCl4-induced liver fibrosis." (PMID 35582617, 2022). "Our previous study evidenced well the anti-liver fibrosis effects of GF on the TAA-induced liver fibrosis model via the enhancement of hepatic Sirt1 activation." (PMID 36670959, 2022). "It was noteworthy that the improvement effect of curcumol on liver fibrosis in mice was mediated by Sirt1." (PMID 35582617, 2022). "For instance, pterostilbene, a natural polyphenol, decreases liver fibrosis by increasing SIRT1 expression through downregulation of miR-34a." (PMID 35883477, 2022). "All together, these results indicated that the ameliorative effect of curcumol on liver fibrosis in mice depended on Sirt1-mediated necroptosis." (PMID 35582617, 2022). "Recent studies emphasize that overexpressing or activating SIRT1 inhibits hepatic senescence and activation of HSCs to ameliorate liver fibrosis." (PMID 33522656, 2021). "Taken together, GF attenuated liver fibrosis through AMPK/SIRT1 pathway as well as Nrf2 signaling cascades." (PMID 34829709, 2021). "Some recent evidence reports that the activation of SIRT1 confers protective effects on hepatic senescence and HSCs activation to ameliorate liver fibrosis." (PMID 33522656, 2021). "SIRT1, a validated miR-132 target, is involved in inflammatory and fibrotic pathways, and decreased expression of SIRT1 was reported in liver fibrosis." (PMID 34458001, 2021). "Alterations in miR-34a expression levels have been shown to be closely related to liver fibrosis; activation of the miR-34a/SIRT1 pathway plays a critical role in fructose-induced liver fibrosis via the TGF-β1/Smads pathway in rats." (PMID 33880382, 2021). "For instance, it has been reported that SIRT1 knockout in hepatocytes aggravates inflammatory response in the liver, and SIRT1 can also participate in liver fibrosis by regulating the TGF-β signaling pathway." (PMID 33906673, 2021). "In short, MALAT1 promotes HSC activation by blocking SIRT1-mediated inhibition of the TGF-β signaling pathway in hepatic fibrosis." (PMID 35145971, 2021). "These phenomena suggest a role for MALAT1 in mediating the expression as well as the function of SIRT1 in regulating liver fibrosis." (PMID 34899344, 2021). "As a positive drug treatments Silymarin 50 mg/kg, also well showed beneficial properties on TAA-induced liver fibrosis by controlling of SIRT1/AMPKα signaling pathways with statistical significances as compared with the control group (p < 0.01)." (PMID 34829709, 2021).
liver fibrosis (continued). "In concordance with our finding of increased miR-132 and decreased SIRT1 in liver fibrosis, an inverse correlation between miR-132 and SIRT1 expression was found in HCC samples in the TCGA database." (PMID 34458001, 2021). "Others have shown decreased SIRT1 levels in mouse models of liver fibrosis, in patients with cirrhosis, and in activated HSCs, as well as a role in the liver fibrosis." (PMID 34458001, 2021). "Other negative regulators of SIRT1 in the course of liver fibrosis can be micro-RNAs, such as miR-200a and miR-9a-5p." (PMID 34899370, 2021). "Subsequently, several parameters about liver fibrosis and intestinal mucosal barrier dysfunction were detected in SIRT1‐overexpressed NAFLD mice." (PMID 32324317, 2020). "Collectively, GRHL2 played a contributory role in NAFLD by exacerbating liver fibrosis and intestinal mucosal barrier dysfunction with the involvement of miR‐200‐dependent SIRT1 and the MAPK signalling pathway." (PMID 32324317, 2020). "Even though SIRT1 is the most characterized member of this family in liver fibrosis, there are others sirtuins involved in the hepatic fibrogenesis." (PMID 33086678, 2020). "Recently, sirtuins have been proposed as new therapeutic targets for the treatment of liver fibrosis, being SIRT1 the most well-characterized." (PMID 33086678, 2020). "In the present study, the downregulation of SIRT1 protein by EX-527 led to a protective effect against liver fibrosis in HFD-induced diabetic rats." (PMID 32365537, 2020). "We demonstrated that SIRT1 activation protects against ER stress, providing grounds for its use in the development of therapies in liver fibrosis." (PMID 30455644, 2018). "In summary, MALAT1 can promote the HSC activation through blocking the SIRT1 mediated inhibition of TGF-β signaling pathway in the progression of hepatic fibrosis." (PMID 30534359, 2018). "In this study, we found that SIRT1 expression was significantly decreased during BDL-induced liver fibrosis." (PMID 30455644, 2018). "The molecular mechanism of SalA against BDL-induced liver fibrosis involves SIRT1 deacetylating HSF1, resulting in a decrease in ER stress and liver fibrosis." (PMID 30455644, 2018). "Previous studies showed that MALAT1is involved in regulation of SIRT1 signaling that contributed to apoptosis and reversion of activated LX-2 cells in liver fibrosis." (PMID 29100395, 2017). "Here we report that transcriptional repression of SIRT1 by PIAS4 contributes to liver fibrosis in response to excessive glucose." (PMID 27323886, 2016). "Subsequently, SIRT1 expression decreased in the CCl4-induced liver fibrosis rats, but SRT1720 treatment reversed this downregulation." (PMID 27387128, 2016). "Lentivirus-mediated delivery of short hairpin RNA (shRNA) targeting PIAS4 in mice ameliorated MCD diet induced liver fibrosis by normalizing SIRT1 expression in vivo." (PMID 27323886, 2016). "In fact, another widely used SIRT1 activator, resveratrol, has also been reported to attenuate liver fibrosis in animal models." (PMID 27387128, 2016).
liver fibrosis (continued). "Here we report that PIAS4 mediates SIRT1 repression in cultured HSCs exposed to high glucose and in a mouse model of NASH-associated liver fibrosis." (PMID 27323886, 2016). "Resveratrol may restore SIRT1 expression, normalize C/EBPα acetylation and bile acid homeostasis, and reduce hepatic arsenic accumulation, thereby alleviating liver fibrosis." (PMID 42278648, 2026). "Additionally, carvacrol and cilostazol co-administration was found to ameliorate ethanol-induced liver fibrosis through the SIRT1/Nrf2/HO-1 pathway, exerting antioxidant, anti-inflammatory, and anti-apoptotic effects." (PMID 40052151, 2025). "Notably, in both carbon tetrachloride (CCl4)- and bile duct ligation (BDL)-induced mouse models of liver fibrosis, a marked downregulation of SIRT1 expression has been observed." (PMID 41281762, 2025). "According to recent data, SIRT1 activation protects against liver fibrosis and inflammation." (PMID 40552161, 2025). "SEMA significantly reduced the severity of liver fibrosis induced by TAA through SIRT1 activation." (PMID 41111129, 2025). "SIRT1 regulates the expression of multiple downstream genes by controlling transcription factors, such as Nrf2, which modulates the transcription of antioxidant enzymes to affect cellular oxidative stress and has a well‐documented role in liver fibrosis." (PMID 41498016, 2025). "It was, therefore, hypothesized that sotagliflozin may have hepatoprotective effects through the modulation of the Sirt1/Nrf2 and PI3K/AKT pathways, causing a decline in oxidative stress, inflammation, and apoptosis in hepatic fibrosis." (PMID 41498016, 2025). "In carbon tetrachloride (CCl4)-induced hepatic fibrosis rat models, SIRT1 overexpression attenuates the conversion of macrophages to the pro-inflammatory M1 type and inhibits the release of inflammatory cytokines via downregulation of the nuclear factor kappa B (NF-κB)/NLRP3 pathway." (PMID 38543036, 2024). "For investigating this hypothesis, we explored the role of a recently discovered SIRT1/2 inhibitor, Tenovin-1, in oxidative stress, inflammation, and fibrosis associated with high-fat diet (HFD)-induced hepatic fibrosis." (PMID 38993557, 2024). "Additionally, animal experiments have demonstrated that Gardeniae Fructus can mitigate thioacetamide-induced liver fibrosis in mice via the AMPK/SIRT1/NF-κB and Nrf2 signal pathways." (PMID 39703394, 2024). "Thus, we suspect that age‐dependent defects of SIRT1 accelerate the development of liver fibrosis via a mechanism involving altered FGF21." (PMID 36999514, 2023). "The present study demonstrates that the age‐dependent decline in SIRT1 is linked to NLRP3 signaling which leads to severe and persistent liver fibrosis during liver injury, even after cessation of injury, in an experimental model of hepatotoxin‐induced liver fibrosis." (PMID 36999514, 2023). "Taken together, the results indicated that activating SIRT1 in macrophages could reverse activation of HSCs through relieving the inflammation of macrophages, thereby alleviating liver fibrosis." (PMID 37057212, 2023). "In addition, SIRT1 depletion in hepatic stellate cells aggravates hepatic fibrosis following bile duct ligation in young mice." (PMID 38034869, 2023).
liver fibrosis (continued). "Salvianolic acid may prevent liver fibrosis brought on by bile duct ligation by triggering the SIRT1/heat shock factor 1 (HSF1) signaling pathway." (PMID 36985782, 2023). "Besides, CCl4 triggered the high level of LPS in plasma in rat liver fibrosis, which was inhibited by overexpressing SIRT1." (PMID 37057212, 2023). "In addition, the SIRT1 inhibitor EX527 reversed the inhibition effects on ECM accumulation and inflammatory response in LX-2 cells after FAT10 silencing, suggesting that SIRT1 protein was involved in FAT10-mediated liver fibrosis." (PMID 37057207, 2023). "Further, we transferred SIRT1 adenovirus vector to CCl4-induced rat liver fibrosis models." (PMID 37057212, 2023). "As an NAD+ dependent class III deacetylase, Sirt1 plays vital physiological function in a variety of diseases such as tumors and metabolic diseases, including liver fibrosis." (PMID 35582617, 2022). "Taken together, our research provides new insights into the effects of progerin-related nucleophagy in LSEC defenestration and suggests a new strategy for reversing LSEC defenestration and liver fibrosis by promoting progerin clearance via the SIRT1-mediated deacetylation of nuclear LC3." (PMID 36497176, 2022). "Additionally, the combinations of the active compounds from GF and silymarin need to be explored for their effects on liver fibrosis conditions by the regulation of hepatic Sirt1 activities." (PMID 36670959, 2022). "Interestingly we found out that GS modulates Sirt1 in the liver tissue during TAA-induced liver fibrosis, mainly controlling oxidative-stress-mediated hepatocyte deaths and liver fibrosis by the inhibition of HSCs’ activation, respectively." (PMID 36670959, 2022). "In vivo, premature senescence was triggered by oxidative stress during CCl4‐induced HSECs defenestration and liver fibrogenesis, whereas overexpressing SIRT1 with adenovirus vector lessened premature senescence to relieve CCl4‐induced HSECs defenestration and liver fibrosis." (PMID 33522656, 2021). "Taken together, SIRT1 overexpression may inhibit liver fibrosis and intestinal mucosal barrier dysfunction in NAFLD mice." (PMID 32324317, 2020). "MALAT1 expression is upregulated and regulates sirtuin 1 (SIRT1) in liver fibrosis." (PMID 32098245, 2020). "In addition, SIRT1 levels were markedly decreased in mouse models of hepatic fibrosis, cultured HSCs undergoing activation, and in cirrhosis patients." (PMID 32365537, 2020). "Although SIRT1 plays a pivotal role in the prevention of HFD-induced liver fibrosis development, the functional role of SIRT4 in the progression of hepatic fibrosis remains unknown." (PMID 32365537, 2020). "In this study, we identified the functions of GRHL2 in NAFLD and further found that SIRT1 down‐regulation induced by GRHL2‐dependent miR‐200 or MAPK signalling pathway activated by GRHL2 exacerbated liver fibrosis and intestinal mucosal barrier dysfunction in NAFLD." (PMID 32324317, 2020). "Interestingly, the results observed in the present study also indicated that SIRT1 elevation ameliorated liver fibrosis and intestinal mucosal barrier dysfunction in NAFLD mice." (PMID 32324317, 2020). "The beneficial effects of SIRT1 in controlling hepatic lipid metabolism, regulation of oxidative stress and inflammation via deacetylating of some transcription factor against development of hepatic fibrosis is well established." (PMID 32365537, 2020). "It was found that SIRT1 signaling pathway has a role in apoptosis in liver fibrosis." (PMID 30514825, 2019). "Additionally, glucagon can promote SIRT1 inhibition of liver inflammation, and inflammation is the most critical factor leading to the progression of liver fibrosis." (PMID 30995792, 2019). "Moreover, we determined that the SIRT1/HSF1 pathway is involved in the protective effects of SalA against BDL- induced liver fibrosis." (PMID 30455644, 2018).